PIPSL (PIP5K1A and PSMD4 like (pseudogene))
Description:
Has negligible PIP5 kinase activity. Binds to ubiquitinated proteins.
Synonyms: PIP5K1A-PSMD4; PIP5K1P3; formerly PSMD4P2; PIP5K1L1
Gene: Transcribed processed pseudogene on chromosome 10 (93,958,808 to 93,961,540, reverse strand). Ensembl gene ENSG00000180764.
Subcellular location: Cytoplasm